ALB (albumin)
Diseases named in the same sentence as ALB in open-access papers (continued):
Sharing a sentence is not in itself a finding about the gene and the disease.
pancreatic cancer (continued). "Physiological levels of albumin, the major protein in circulation, enable pancreatic cancer cells to proliferate under limiting glutamine concentrations." (PMID 30967008, 2019). "Interestingly, a study has described how a mutation to the KRAS gene in pancreatic cancer cells display elevated levels of macropinocytosis, a form of endocytosis, of proteins such as albumin, a fact which may be behind the recent success of Abraxane in treating advanced pancreatic cancer." (PMID 29360800, 2018). "In this study, the overall survival (OS) of advanced pancreatic cancer patients was compared using different levels of bilirubin and ALB." (PMID 30474926, 2018). "Abraxane, a 130 nM simple albumin NP-bound paclitaxel that is currently licenced for use in breast, lung and pancreatic cancers." (PMID 28695300, 2017). "Survival rates of pancreatic cancer in the community are affected by many factors, such as age, sex, type of cancer, staging at the time of diagnosis, serum albumin level, and tumor size." (PMID 29379588, 2017). "This study aimed to assess the effects of bovine serum albumin (BSA) nanoparticles carrying the hMDA-7 gene (BSA-NP-hMDA-7) in the treatment of pancreatic cancer." (PMID 28985230, 2017). "Tubulin binding agents such as albumin-bound formulations of paclitaxel have also been approved by the FDA for pancreatic cancer treatment." (PMID 27278358, 2016). "The study provides evidence that the albumin-integrated defensin bestowed with intensive macropinocytosis attribute is highly effective against K-Ras mutant pancreatic cancer." (PMID 27517152, 2016). "In this study, pancreatic cancer MIA PaCa-2 cells showed more efficient micropinocytosis-mediated cellular uptake of human serum albumin, compared with wild-type K-Ras-expressing BxPC-3 cells; this is in conformity with that of previous report." (PMID 27517152, 2016). "Paclitaxel is such an example: by linking the drug taxol or the synthetic derivates to nanocore systems such as human serum albumin results in Abraxane, a nanotechnology recently also applied for the treatment of pancreatic cancer." (PMID 27993133, 2016). "The macropinocytosis inhibitor EIPA can significantly reduce the uptake of a large amount of albumin and inhibit tumor xenograft growth of pancreatic carcinoma MIA PaCa-2 cells that display intensive macropinocytosis." (PMID 27517152, 2016). "We note that the only FDA-approved nanotherapeutic currently available for pancreatic cancer is Abraxane, an albumin-bound form of paclitaxel." (PMID 26046360, 2015). "A study determined clinical and laboratory predictors of mortality in pancreatic cancer and found that upon multivariate analysis low serum albumin and an increased white blood cell (WBC) count independently predicted survival of less than 6 months." (PMID 21176210, 2010). "Additionally, studies of older patients with pancreatic cancer have reported that those with a low CRP/albumin ratio exhibit good treatment responses." (PMID 39870769, 2025). "Between 2013 and 2022, patients with (borderline) resectable pancreatic cancer with vessel contact who received 5-fluorouracil with leucovorin, oxaliplatin, and irinotecan or gemcitabine and nanoparticle albumin-bound paclitaxel as initial treatment following surgery were included." (PMID 39808212, 2025). "Lasso Cox regression showed that A-SII score, number of organ metastases, tumor size, chemotherapy, targeted therapy, Neutrophil-to-albumin ratio, and lactate dehydrogenase were independent prognostic factors for the OS of advanced pancreatic carcinoma patients." (PMID 40265018, 2025). "In summary, inflammatory biomarkers in combination with albumin compared to other conventional nutritional parameters may represent earlier and more sensitive parameters in the prognostication of pancreatic cancer." (PMID 38539528, 2024). "Therefore, nano-delivery systems based on serum albumin are widely used in pancreatic cancer treatment." (PMID 39070787, 2024).
pancreatic cancer (continued). "Abraxane® is currently the only albumin-bound drug approved to treat metastatic pancreatic cancer." (PMID 39070787, 2024). "This trial compared investigational hand therapy intervention with a traditional occupational therapy approach to prevent chemotherapy-induced peripheral neuropathy in patients with pancreatic cancer receiving gemcitabine and albumin-bound paclitaxel containing regimens." (PMID 39436905, 2024). "In the univariate analyses, age, ECOG performance status, tumor staging, elevated CA 19-9 levels, hemoglobin levels, albumin levels, CRP levels, selected treatment modalities, and the presence of fatigue were significantly associated with the survival of pancreatic cancer." (PMID 39115263, 2024). "Ongoing clinical trials of albumin NPs in pancreatic cancer." (PMID 39070787, 2024). "This trial compared investigational hand therapy intervention (Investigational) compared with a traditional occupational therapy approach (Traditional) to prevent CIPN in patients with pancreatic cancer receiving gemcitabine and albumin-bound paclitaxel containing regimens." (PMID 39436905, 2024). "The five-year survival rate of pancreatic cancer in China is only 7.2%, which is the lowest among all cancers and the use of combined paclitaxel albumin, capecitabine, and digital has been the clinical standard treatment for advanced pancreatic cancer since 1997." (PMID 37152980, 2023). "For example, recent data from Virginia Commonwealth University Health demonstrated that fewer Black patients were eligible for pancreas cancer clinical trials when compared to White patients, largely due to low albumin levels and co‐existing infectious disease." (PMID 37151163, 2023). "These tools, in conjunction with other parameters, including BMI and other serum markers, e.g., albumin and prealbumin, may help manage strategies for improving the nutritional status of patients with pancreatic cancer." (PMID 37568634, 2023). "The GNRI measured with clinically available weight and albumin levels may predict overall survival and prognosis among patients with pancreatic cancer." (PMID 36145174, 2022). "Although the intriguing connection between KRAS genotype and FcRn expression level remains blurred, the two critical regulators of albumin metabolism have demonstrated synergistic impacts on the sensitivity of pancreatic cancer to albumin-conjugated drugs both in vitro and in vivo." (PMID 35154489, 2022). "In patients with pancreas cancer, BMI < 25.0 kg/m2 was significantly associated with OS (P = 0.025), while albumin < 35.0 g/L was not (P = 0.086)." (PMID 35773692, 2022). "This prospective cohort study was designed to explore whether preoperative BMI and serum albumin levels affected OS in patients undergoing PD for pancreatic cancer or periampullary cancer." (PMID 35773692, 2022). "The Geriatric Nutritional Risk Index (GNRI) may also be useful in determining the nutritional status of patients with pancreatic cancer and predicting survival utilizing clinically available data, as it is calculated using serum albumin and weight." (PMID 36145174, 2022). "Current guidelines routinely recommend neoadjuvant therapy for all patients with borderline resectable pancreatic cancer in well physical condition, including nanoparticle albumin-bound paclitaxel plus gemcitabine and Combined with sequential chemoradiotherapy or modified FOLFIRINOX solution." (PMID 36059612, 2022). "The extracellular proteins that are present in the tumor microenvironments, including albumin, could enhance the growth of pancreatic tumors by serving as an important source of amino acids." (PMID 33401771, 2021). "Similarly, another retrospective study of 53 patients with pancreatic cancer indicated that patients with preoperative albumin lower than 2.8 g/dl (p = 0.021) had a poor prognosis." (PMID 34136406, 2021).
pancreatic cancer (continued). "Two studies described impaired albumin synthesis with a normal survival in cancer including leukemia and lymphoma patients, whereas another group described normal albumin synthesis rates in cachectic individuals with pancreatic cancer." (PMID 35847697, 2020). "Furthermore, the mouse pancreatic cancer cell line KRPC can derive amino acids from the proteolytic degradation of extracellular albumin to sustain their proliferation." (PMID 32756454, 2020). "Serum albumin is often considered a surrogate marker for nutritional status, ‘general fitness’, and ability to recover following major abdominal surgery, and has been assessed in numerous trials on resectable pancreatic cancer." (PMID 33008332, 2020). "Second, in the past 5 years, there were increasing number of the different chemotherapeutic regimens for pancreatic cancer, including gemcitabine monotherapy or combination with other agents (e.g., oxaliplatin and albumin-bound paclitaxel), or even more toxic regimen of FOLFIRINOX." (PMID 32565799, 2020). "Finally, human serum albumin (HSA) chemically conjugated to PEG dendrimers was suggested as a functional biomaterial for the induction of apoptosis in pancreatic cancer." (PMID 31546921, 2019). "Moreover, a sophisticated approach using tissue microimplants that release fluorescent macromolecules allowed the monitoring of macropinocytosis as well as albumin catabolism in murine pancreatic tumours." (PMID 30967008, 2019). "In addition, combination chemotherapies, such as regimens combining DFX, GEM, and albumin-bound paclitaxel, possibly have therapeutic advantages over albumin-bound paclitaxel with GEM in pancreatic cancer." (PMID 29983871, 2018). "We hypothesized that bovine serum albumin (BSA) nanoparticles carrying the hMDA-7 gene will be effective in the treatment of pancreatic cancer." (PMID 28985230, 2017). "Nanomedicines are apparently more beneficial in the treatment of pancreatic cancer compared to small molecules, and several nanodrugs have been approved by FDA in combination therapy for advanced pancreatic cancer such as albumin-bound paclitaxel (Abraxane) and liposomal irinotecan (Onivyde)." (PMID 29042665, 2017). "Abraxane is an albumin bound formulation of paclitaxel where albumin favors drug internalization and indeed, according to a recent report, this formulation showed promising results in advanced pancreatic cancer." (PMID 26571380, 2015). "Indeed, the efficacy of gemcitabine for treating pancreatic cancer can be improved with the co-administration of Nanoparticle albumin-bound (nab)-paclitaxel." (PMID 25628149, 2015). "BACKGROUND: Gemcitabine plus albumin-bound paclitaxel is widely used as first-line therapy for unresectable pancreatic cancer, but it is frequently complicated by chemotherapy-induced peripheral neuropathy, which may lead to functional impairment and treatment modification." (PMID 41947190, 2026). "Moreover, the use of some plant nanoparticles in tumor diseases provides insights for other diseases; for example, albumin-bound paclitaxel, a nanoformulation of paclitaxel bound to albumin, has shown promising results in improving survival rates in pancreatic cancer clinical trials." (PMID 38556857, 2024). "However, new albumin-based nanomedicines for pancreatic cancer are also in development." (PMID 39070787, 2024). "Hence, it would be desirable to develop albumin-encapsulated liposomes that could facilitate the extent of penetration into this fibrotic extracellular matrix in pancreatic cancer." (PMID 33810483, 2021).
pancreatic cancer (continued). "In addition, the new pharmaceutical form of paclitaxel such as nanoparticle albumin-bound paclitaxel or albumin‐free nanosomal paclitaxel lipid suspension in combination with gemcitabine has demonstrated significant efficacy in the treatment of pancreas cancer." (PMID 34760094, 2021). "Therefore, this study is conducted with the aim to identify whether baseline bilirubin and ALB have protective properties against advanced pancreatic cancer and whether they have the potential to act as predictors for survival and prognosis." (PMID 30474926, 2018). "Therefore, the CAR, a combined pattern of both CRP and albumin, may reveal the outcome of pancreatic cancer in a better way." (PMID 28592881, 2017). "The most promising approach inhibiting this interaction so far involves a soluble EphB4 ECD conjugated to human serum albumin (EphB4-ECD-HSA), this has shown anti-angiogenic effects on pancreatic tumours in Rip1-Tag2 mice, which could be improved with Dll4-Notch blockade using Dll4-ECD-Fc." (PMID 26620208, 2016). "For example, there are studies that focus on clinical data from patients with pancreatic cancer, using clinical variables (such as tumor stage, CA19–9 levels, albumin levels, etc.)to predict patients ‘OS." (PMID 41208979, 2025). "Recently, albumin-myosteatosis gauge (AMG) has been proposed as a novel skeletal muscle-related marker in colorectal and pancreatic cancer, with low pre-treatment AMG levels reported to worsen prognosis." (PMID 40075586, 2025). "Therefore, in this study, albumin and SII were combined to obtain the A-SII score to make up for the deficiency of a single marker, and a nomogram was constructed on basis of the Lasso Cox regression for predicting the OS of advanced pancreatic carcinoma patients." (PMID 40265018, 2025). "Univariate and multivariate Cox regression analyses identified albumin and SII as independent prognostic factors in advanced pancreatic carcinoma (P < 0.05)." (PMID 40265018, 2025). "In our human cohort of stage 0-IV pancreatic cancer patients, the serum TNC concentration was positively correlated with the NLR and negatively correlated with the ALB concentration, indicating that TNC levels are related to inflammation." (PMID 38797735, 2024). "Background/Objectives: The survival rate of patients with pancreatic cancer (PC) has improved gradually since the introduction of FOLFIRINOX (FFX) and gemcitabine + albumin-bound paclitaxel (GnP) regimens." (PMID 38892939, 2024). "Studies have shown that IGF2BP3, ALB, KRT6A, and REG3 partake in the pancreatic cancer origin and development." (PMID 37505298, 2024). "Overall, the proposed combination therapy, facilitated by novel albumin-based NPs and a PLGA-PEG-PLGA hydrogel, represents a promising advancement in pancreatic cancer treatment, offering a balance between therapeutic effectiveness and reduced systemic impact." (PMID 39770508, 2024). "The standard treatment for pancreatic cancer includes FOLFIRONOX (a blend of 5-fluorouracil, calcium folinic acid, irinotecan, and oxaliplatin) or gemcitabine with albumin-conjugated paclitaxel." (PMID 38305809, 2024). "In pancreatic cancer tissues, ADM, KRT17, and ANXA1 protein levels surpassed those in normal samples, while C7 and ALB protein levels exhibited a declining trend, in accordance with the findings from qRT-PCR and bioinformatics analysis." (PMID 37941546, 2023). "In patients with septic shock, acute renal injury, and palliative pancreatic cancer, NPAR, which integrates albumin and NLR, is employed as a systemic inflammation predictor." (PMID 37525801, 2023). "Later, in the year 2005 paclitaxel as an albumin formulation known as Abraxane was approved for the treatment of NSCLC, breast, and pancreatic cancers." (PMID 38112935, 2023).
pancreatic cancer (continued). "The Chinese guidelines for comprehensive diagnosis and treatment of pancreatic cancer recommend several agents for neoadjuvant chemotherapy, including FOLFIRINOX, gemcitabine (GEM) + albumin-bound paclitaxel, GEM + S-1 or GEM alone." (PMID 37672511, 2023). "Albumin-conjugated paclitaxel (Abraxane®), which was approved by the FDA for treating metastatic breast, non-small-cell lung, and pancreatic cancers, is expected to be effectively taken up by hypoxic HCC cells." (PMID 35177645, 2022). "In terms of pancreatic cancer, one of the widely described inflammation-based parameters is CRP/albumin ratio (CAR)." (PMID 35740504, 2022). "Albumin-based nanomedicines, as representative examples, have been approved by the FDA and taken the lead in clinical practice to treat breast, lung, and pancreatic cancer, highlighting the great prospects of therapeutics in this category." (PMID 36015215, 2022). "This study showed that albumin in the circulation is internalized, catabolized, and utilized by RAS-transformed pancreatic cancer cells." (PMID 35177645, 2022). "AbraxaneTM is a nanoparticle albumin-bound formulation of paclitaxel (referred to as nab-PTX), that is currently used as the first-line treatment for advanced pancreatic cancer in combination with gemcitabine." (PMID 35154489, 2022). "A previous study supported the use of a combination of two markers, IGF-1 and albumin, with CA19-9 to increase the sensitivity to 93.6% in pancreatic cancer." (PMID 36555927, 2022). "Albumin-bound paclitaxel (nab-paclitaxel) was approved by the Food and Drug Administration (FDA) in 2013 for the treatment of pancreatic cancer in combination with gemcitabine." (PMID 35658912, 2022). "Based on in vivo mice experiments using human serum albumin-conjugated soluble EphB4, it was confirmed that EphB4 could serve as a potential therapeutic target in pancreatic ductal adenocarcinoma and further research is necessary to prove its efficacy in the treatment of pancreatic cancer patients." (PMID 34298619, 2021). "The ratio of C-reactive protein (CRP) to albumin (CAR) has a significant correlation with postoperative complications and acts as a predictor in patients with pancreatic cancer and colorectal cancer." (PMID 33727917, 2021). "Albumin based nanoparticles loaded with lapatinib (triple negative breast cancer and HER2-positive breast cancer), gemcitabine (pancreatic cancer), siRNAs (breast and lung cancers), gold nanoparticles for NSCLC, photosensitizers are also being developed." (PMID 30634580, 2019). "Gemcitabine was the first line therapy for neoadjuvant chemotherapy for locally advanced pancreatic cancer during that time, however, its ORR was unsatisfactory compared with FOLFIRINOX or gemcitabine+albumin-bound paclitaxel regimens." (PMID 31601220, 2019). "GEM-sensitive (GEM-S) and GEM-resistant (GEM-R) pancreatic carcinoma xenograft models were established, and GEM monotherapy and GEM plus nanoparticle albumin-bound paclitaxel (nab-PTX) doublet therapy were administered to GEM-S/R tumor-bearing mice." (PMID 32064236, 2019). "Although previous studies demonstrated that elevated C-reactive protein to albumin ratio (CAR) predicted poor prognosis in various solid tumors, little was known about the prognostic value of CAR in patients with advanced pancreatic cancer (APC)." (PMID 28592881, 2017). "Drug treatment promoted eosinophils in pancreatic cancer patients (p = 0.015), increased potassium (p = 0.013), and decreased albumin (p = 0.016) in CRC patients; however, these effects did not remain significant after false discovery rate (FDR) correction." (PMID 42088573, 2026). "In addition, there are rarely studies that investigated the relationship between albumin combined with SII (A-SII) score and prognosis of advanced pancreatic carcinoma." (PMID 40265018, 2025).